CXCR2 (C-X-C motif chemokine receptor 2)
Diseases named in the same sentence as CXCR2 in open-access papers (continued):
Sharing a sentence is not in itself a finding about the gene and the disease.
tumor (continued). "In the CCSPcre/K-rasG12D K-ras mutant mouse model of lung cancer the selective inhibition of CXCR2 led to a reduction in neutrophil infiltration in the lungs and diminished tumor growth." (PMID 27618112, 2016). "In this report, we reveal a previously unidentified tumor cell-autonomous role of KRAS(G12D)-induced CXCR2 signaling in mediating growth of neoplastic PDAC cells." (PMID 26771140, 2016). "Recently, studies demonstrated that CXCR2 play a critical role in tumor invasion and metastases in many types of cancer, such as lung cancer, melanoma, colon cancer, and pancreatic cancer." (PMID 27807540, 2016). "Inhibition of CXCR2 dramatically decreased angiogenesis and tumor growth by suppressing AKT signaling." (PMID 27058419, 2016). "The expression of angiogenic factors such as CXCL1, CXCL5, and CXCL8 was increased in the peripheral blood mice that overexpressed IL-17, whereas CXCR-2 blocked the angiogenic effects of IL-17, which suggests that IL-17 promoted tumour angiogenesis via CXCR-2." (PMID 27872514, 2016). "CXCR2 knockout mice significantly reduced tumor burden in some cancer models such as prostate cancer, lung cancer and renal cancer." (PMID 27723802, 2016). "Overexpression and binding of CXCL1 and its receptor CXCR2 has been shown to promote tumour invasion." (PMID 27028996, 2016). "In AB1 and LCC mouse models the administration of CXCR2 antagonist SB225002 reduced tumor growth likely by limiting neutrophil recruitment and their role in immunosuppression and angiogenesis." (PMID 27618112, 2016). "This is consistent with previous studies which showed that tumour growth and invasion was inhibited when CXCR2 is down-regulated." (PMID 27028996, 2016). "In conclusion, this study is the first to demonstrate that TNF‐α, a key mediator in the inflammatory tumour microenvironment, strongly up‐regulated CXCR2 and CXCR3 to enhance migration, invasion, EMT and sphere formation of RCC cells." (PMID 27297979, 2016). "One of the main findings of the current study was that inhibiting CXCR2 genetically or pharmacologically decreased KRAS(G12D)-induced tumor cell growth." (PMID 26771140, 2016). "In patients with hepatocellular carcinoma the presence of high expression of CXCR2 and its ligands CXCL5 and CXCL8 (IL-8) on tumor cells are associated with neutrophil recruitment and neoplastic cell spreading." (PMID 27618112, 2016). "This suggests that CXCR1 and CXCR2 signaling provides the surviving re-grown tumor cells with a paracrine loop from IL-8 and CXCL-1 to maintain tumor cell survival." (PMID 27379204, 2016). "Correspondingly, the expression of CXCR2 is the highest on neutrophils from BM and blood, and is downregulated after reaching the tumor." (PMID 28066438, 2016). "A CXCR2 antagonist inhibits proliferation and invasion of CRC cells in an in vitro assays and the growth of tumor xenografts in immune-deficient mice." (PMID 26320187, 2015). "Several studies have supported that the function of CXCR1 and CXCR2 in tumor angiogenesis and of these two receptors, CXCR2 is the receptor most likely involved in IL-8 promoted angiogenesis in endothelial cells." (PMID 26559818, 2015). "CXCR2 promotes tumor growth through recruiting pro-tumorigenic neutrophils and stimulating angiogenesis." (PMID 26320187, 2015). "CXCR2 has been shown to promote cell proliferation, invasion, and migration, while CXCR2 inhibitors have been reported to reduce tumor growth." (PMID 26503598, 2015). "Patients with CXCR2-positive tumors showed a significant tendency to develop distant metastases, and this result is consistent with that of several studies reporting that an IL-8 and CXCR2 network promotes tumor invasion, migration, and metastasis." (PMID 26231560, 2015). "High CXCR2 expression correlated with poor tumor differentiation (p = 0.021), increased tumor depth (p < 0.001), lymph node metastasis (p < 0.001) and advanced TNM stage (p < 0.001)." (PMID 26497045, 2015).
tumor (continued). "IL-8 overexpression increases CXCR1 and CXCR2 expression on tumor cells, endothelial cells, and immune related cells (neutrophils and macrophages) resident in tumor tissue." (PMID 26504364, 2015). "Our results show that the combined CXCR2 inhibition with sorafenib effectively alleviated tumor progression and provided extended therapeutic benefit." (PMID 26414070, 2015). "The combination of CXCR2 inhibitor with sorafenib led to a synergistic inhibition of cell growth in vitro, and further stabilized tumor progression following sorafenib in vivo." (PMID 26414070, 2015). "By contrast, a recent study reported the induction of CXCR2 and CXCR2 ligand expression by oncogenic K-ras, which reinforces senescence in vitro and suggests that it acts as a tumor suppressor." (PMID 26503598, 2015). "CXCR1 and CXCR2, receptors for IL-8, are highly expressed in tumor and endothelial cells and potentially mediate the angiogenic function of IL-8 in tumor angiogenesis." (PMID 26559818, 2015). "Our present study identified that intratumoral CXCR2 expression correlates with gastric cancer progression, tumor differentiation and lymph node metastasis and can be utilized as a novel prognostic factor for patient outcomes." (PMID 26497045, 2015). "In hepatocellular carcinoma mouse model, it was reported that IL17, majorly produced by Vγ4+γδT cells, induced CXCL5 production by tumor cells, which enhance migration of MDSCs (myeloid-derived suppressor cells) expressing CXCR2 to the tumor site." (PMID 25699053, 2015). "CXCR2 is another critical component of tumor cell behavior and its expression in endothelial cells favors tumor angiogenesis." (PMID 26320187, 2015). "IL-8 activates the CXCR1 and CXCR2 CK receptors of neutrophils implicating them in development and promotion of tumor progression and numerous inflammatory disorders." (PMID 25878893, 2015). "Pharmacological inhibition of CXCL1’s cognate receptor CXCR2 normalizes tumour vascularization and microenvironment and reduces tumour burden." (PMID 25734337, 2015). "Intratumoral CXCR2 expression was evaluated with immunohistochemistry on tissue microarrays containing tumor samples of 357 gastric cancer patients from a single center." (PMID 26497045, 2015). "CXCR1 and CXCR2 together with cognate chemokines are significantly upregulated in a number of cancers, where they act as key regulators of tumor cell proliferation, metastasis, and angiogenesis." (PMID 26087179, 2015). "CXCR2 antagonist treatment was conducted in two ways: first, we treated the mice 1 week after AdCre tumour induction." (PMID 25734337, 2015). "In this present study, we showed that compared to HCC tissue and tumor-adjacent normal tissues, the peri-tumoral stroma exhibited the highest density of infiltrating CXCR2+ cells, which were mainly CD15+ neutrophils." (PMID 26503598, 2015). "For example, SCH-527123, a CXCR2 antagonist, blocks tumor angiogenesis and proliferation and sensitizes tumor cells to chemotherapy." (PMID 26517517, 2015). "A number of studies have demonstrated that CXCR2 plays a pivotal role in tumor angiogenesis, proliferation and invasion." (PMID 26497045, 2015). "It was reported that overexpression of CXCR2 was correlated with intrahepatic metastasis, portal cancer embolus and tumour-lymph node-metastasis staging of HCC 43–45." (PMID 24268047, 2014). "Accordingly, CXCR2 H-score increased in parallel with histological grade and marginally with tumor stage." (PMID 24593195, 2014). "CXCR2 expression is increased in some tumor types and pharmacological inhibition of CXCR1 and CXCR2 inhibits neutrophil recruitment into A547 lung tumor spheroids resulting in slower tumor growth." (PMID 25372289, 2014). "Our data thus highlight an original option to specifically and finely tune CXCR2 signaling in pathological situations, where aberrantly elevated, such as tumor angiogenesis and inflammation." (PMID 25339290, 2014).
tumor (continued). "CCR7, CCR9, CXCR1, and CXCR2 are also detected in tumor cells and their ligands can induce the chemotaxis of the corresponding receptor-expressing cells." (PMID 24966464, 2014). "In the tumor context CXCR2 has been shown to stimulate neutrophil invasion and angiogenesis, and to prevent stress induced apoptosis of tumor cells." (PMID 25076207, 2014). "Mouse models have also been instrumental in demonstrating that CXCR2 signaling is involved in the recruitment of myeloid-derived suppressor cells into the tumor microenvironment." (PMID 25372289, 2014). "On the other hand, the depletion of CXCR2 delays the replicative senescence and impairs the senescence response to oncogenic signals, suggesting that it acts as a tumor suppressor." (PMID 25011526, 2014). "We further investigated CXCR2 expression and distribution in the spinal cord after tumor cell inoculation." (PMID 24580964, 2014). "Higher expressions of CXCR1, CXCR2, and CXCR4 with their ligands CXCL5, CXCL8, and CXCL12 appear to be associated with tumor angiogenesis, metastasis, and poor survival in NSCLCs." (PMID 25271023, 2014). "Altogether, these results reveal that CXCR2-dependent senescence modulates the role of hPTTG1 overexpression in tumor growth and metastasis." (PMID 22789011, 2012). "The interplay between hPTTG1 overexpression and chemokine C-X-C motif receptor 2 (CXCR2)/p21-dependent senescence in tumor growth and metastasis of MCF-7 cells was investigated by orthotopic transplantation of severe combined immunodeficiency (SCID) mice." (PMID 22789011, 2012). "Taken together, our findings indicate that CXCR2 plays an important role in inhibiting hPTTG1-induced tumor growth and that it is critical for p21 induction." (PMID 22789011, 2012). "To confirm the molecular link between hPTTG1 and CXCR2/p21 signaling, we performed an immunohistochemical (IHC) analysis in mouse tumor samples." (PMID 22789011, 2012). "Moreover, the tumors that did not lose p21 expression (41 (54.67%) of 75) may carry a mutation in a downstream mediator of hPTTG1/CXCR2/p21 signaling to evade senescence, or the hPTTG1/CXCR2/p21-expressing cells may represent only a portion of a tumor composed of heterogeneous cell types." (PMID 22789011, 2012). "Expression of CXCL1, CXCR1 and CXCR2 was elevated in tumour epithelium relative to normal adjacent tissue (P<0.001)." (PMID 21285972, 2011). "We report an increased expression of CXCL1, CXCR1 and CXCR2 in tumour, compared with the surrounding normal epithelium, providing evidence for enhanced autocrine CXC chemokine signalling in these cancer cells." (PMID 21285972, 2011). "Irrespective, the characterisation of CXCL1 and CXCR2 expression in the tumour epithelium provides a functional compensation for the absence of CXCL8." (PMID 21285972, 2011). "This shows that expression of CXCR2 is necessary for PMN-MDSC migration into the primary tumor in vivo." (PMID 21980263, 2011). "Transcriptome analysis of purified tumor-infiltrating immune cells indicated that only PMN-MDSC express Il8rb (also known as CXCR2), the receptor for CXCL1, CXCL2, and CXCL5." (PMID 21980263, 2011). "The chemokine receptor CXCR2 is a major modulator of inflammation, angiogenesis, tumor growth, and wound healing." (PMID 20419088, 2010). "Our results showed a significant association between CXCR2 (+1208) T allele and a large tumor size (P = 0.0001), high SBR tumor grade (P = 0.01), and lymph node metastases (P = 0.0008)." (PMID 20540789, 2010). "Sustained expression of CXCR1 and CXCR2 in tumour tissues was confirmed by immunohistochemical staining (data not shown)." (PMID 19401689, 2009). "Recently, it has beenreported that Gro-β and IL-8 receptor (CXCR2) expressions on tumor cellsare the key mediators responsible forthe breakdown of the endothelial barrier function by enhancing tumor cell forcegeneration and cytoskeletal remodeling dynamics." (PMID 20107573, 2008).
tumor (continued). "Conversely, when KLF4 functions as a tumor‐suppressive factor within the TME, as exemplified in lung adenocarcinoma, it downregulates NF‐κB2 and CXCR2, concomitantly restrains tumor cell invasion, and enhances the infiltration of CD4+ and CD8+ T cells, macrophages, and other immune subsets." (PMID 41532367, 2026). "In pre-clinical models, CXCR2 inhibitors reduced tumor growth as well as vascular development." (PMID 41590248, 2026). "Collectively, these findings suggest that CXCR2-mediated neutrophil recruitment exerts protective, anti-tumor effects and may represent a new prognostic marker for TNBC patients." (PMID 41977328, 2026). "The mechanism of action of this inhibitor may include increasing the accumulation and activation of KIL cells, reducing the tumour accumulation of CXCR2+ MDSCs in mice, or improving the efficacy of T‐cell immunotherapy." (PMID 41503514, 2026). "Furthermore, in orthotopic EO771 tumor model, we demonstrated that primary tumors from Cxcr2–/– and Cfb–/– mice were also smaller after radiotherapy compared with WT mice, with a significant suppression of serum NET level." (PMID 41480760, 2026). "Furthermore, immunofluorescence analysis of tumour tissues from tumour-bearing mice confirmed the coexpression of CXCR2, CPT1A, and CD47, supporting a functional connection between the IL-8/CXCR2 pathway and metabolic regulation." (PMID 41163221, 2025). "Hence, engineering B7-H3 CAR T cells to express the IL-8 receptor CXCR2 significantly improved their tumor infiltration, metabolic activity, and antitumor efficacy." (PMID 41007114, 2025). "In addition, SB225002-mediated inhibition of neutrophil recruitment in the NB tumor microenvironment parallels CXCR2-specific effects observed in other tumor types, further reinforcing its targeted action." (PMID 41155662, 2025). "Likewise, targeted deletion of CXCR 2 in myeloid cells significantly increased anti-tumour immunity by altering the tumour microenvironment." (PMID 40852716, 2025). "Moreover, from day 7 onward, the percentage of neutrophils in the tumor and the expression of CXCR2, a receptor for IL-8, were significantly higher in the treatment group." (PMID 40963981, 2025). "Notably, members of the CXC chemokine family, including CXCL1, CXCL2, CXCL3, CXCL5 and CXCL8, function through the activation of CXCR1 and CXCR2, playing a key role in promoting tumour angiogenesis." (PMID 39161078, 2025). "Due to increased CXCL1 expression in many cancers, CXCR2 transduction into lymphocytes increases tumor infiltration by such modified cells, which was confirmed by experiments on T cells with increased CXCR2 expression, which specifically migrated to ovarian cells." (PMID 40427171, 2025). "In addition, the use of the CXCR2 antagonist AZD5069 in HCC has been demonstrated to reverse long‐term tumor resistance to ICIs." (PMID 40979214, 2025). "Parallel changes in Ki67 expression in tumour-infiltrating CD8+ T cells and infiltration of macrophages were observed in CXCL15-deficient mice, further supporting the regulatory role of the CXCL15/CXCR2 axis." (PMID 41163221, 2025). "Additionally, neutrophils gather in premetastatic niches via CXCR2 or CXCR4-dependent mechanism and release oncostatin M, elastase, and S100A8/S100A9, which causes tumor cell proliferation." (PMID 40016853, 2025). "They express the CCR2, CCR5, and CXCR2 chemokine receptors, which are then mobilized to the blood and tumor by chemokine ligands (CCL2, CCL5, CXCL1-8) and other inflammatory mediators like prostaglandin E2 (PGE2) generated by TME, VEGF, TGF-β, TNF-α, and IL-1β, IL-6, and IL-10." (PMID 40727443, 2025). "CXCR2 is expressed not only on tumor cells but also on T cells." (PMID 40839237, 2025). "Taken together, our data and previously published data strongly demonstrate that CXCR2 ligands are produced in high quantity from PDAC tumors and promote the recruitment and/or retention and differentiation of CXCR2+ MDSCs, which counteract anti-tumor immunity." (PMID 40427538, 2025).
tumor (continued). "CXCL1 and the broader CXCR2 axis play a key role in tumor progression." (PMID 40427171, 2025). "Moreover, tumor cells induce tumor-associated neutrophils to release neutrophil extracellular traps (NETs) through autocrine signaling via IL-8/CXCL8, CXCR1/CXCR2 agonists, G-CSF, and TGF-β pathways." (PMID 40563367, 2025). "At the same time, it also promoted the expression of ALDH1A1 and tumor stemness, while inhibiting CXCR2 or NF-κB could block the tumor promotion effect of IL-8." (PMID 40008905, 2025). "Furthermore, studies have shown that combined treatment with CXCL8/CXCR2 inhibitors, such as SX-682, and ICIs can significantly enhance anti-tumor efficacy by reducing MDSC recruitment." (PMID 40006729, 2025). "Furthermore, combination therapy with SB225002 and cisplatin was synergistically more effective in reducing tumor growth in an orthotopic murine model, and CXCR2 monotherapy prevented enhanced CD8+ T-cell activation." (PMID 40507214, 2025). "CXCL2/CXCR2 axis in tumor-infiltrating myeloid-cells was highly context-dependent." (PMID 40087771, 2025). "Finally, in C57BL/6 model mice implanted with RM-1/CXCR2 tumour cells, TAMs exhibited prominent M2 polarization upon CXCL15 activation." (PMID 41163221, 2025). "Furthermore, IL-8 interacts with its cognate receptors CXCR1 and CXCR2 to promote tumor cell survival and induce epithelial–mesenchymal transition (EMT)." (PMID 41515435, 2025). "Notably, tumor cells were the exclusive source of overexpressed Ccl5 and Cxcl2, while Ccr5 + NK cells and Cxcr2 + macrophages were enriched in the NLRP4-OE TIME, a pattern that persisted throughout tumor progression." (PMID 40087771, 2025). "To investigate whether CXCR2 downregulation contributes to tumor progression by affecting CAF differentiation in vivo, we examined the role of CXCR2 in stromal cells using a murine tumor xenograft model." (PMID 40490643, 2025). "Importantly, TREM2 and CXCR2 directly promote the protumor functions of TAMs, and the inhibition of their expression and activity has been shown to suppress tumor growth and enhance the efficacy of tumor immune therapy." (PMID 41440012, 2025). "Notably, recent studies have shown that CXCR2 is also important for the recruitment of macrophages to the tumour niche." (PMID 40615400, 2025). "The terminally mature N2 subset (CD10+CD16brightCD101+), marked by high CXCR2 expression, generated the strongest ROS response; however, its frequency declined in advanced disease, indicating depletion of mature neutrophils in an inhospitable tumour milieu." (PMID 41451221, 2025). "The interaction between ILC2-derived ligands and CXCR2 on tumor cells leads to apoptosis." (PMID 40497988, 2025). "Such stromal rearrangements might form a barrier physically excluding T cells from penetrating into the tumor core, despite activated inflammatory IL-6 signaling and CXCR2 chemokine gradient." (PMID 40809430, 2025). "In lung cancer, CXCR4 plays a key role in the spread of metastatic cells to the lymph nodes, while in pancreatic cancer, CXCR4 and CXCR2 are involved in mediating tumor-induced inflammation, which creates a favorable microenvironment for tumor cell survival and spread." (PMID 41024311, 2025). "CXCR2 is not only activated by CXCL1 but also by several other CXC chemokines, including CXCL2, CXCL3, CXCL5, CXCL6, and CXCL8, all of which are closely associated with cancer progression and the tumor microenvironment." (PMID 40490643, 2025). "In a recent study was demonstrated that the CXCR2 receptor plays a role in the formation of NETs involved in cancer development, thus targeting CXCR2 axis could inhibit tumor progression." (PMID 38900374, 2025). "The IHC results showed that inhibiting ALDH1A1 or inhibiting IL-8/CXCR2 could suppress the expression of NF-κB and promote apoptosis of tumor cells." (PMID 40008905, 2025). "Blocking this CXCL8/CXCR2/GAG axis is a novel therapeutic strategy that could potentially reverse the tumor immune evasion." (PMID 40124384, 2025).